DUSP4 (dual specificity phosphatase 4)
Diseases named in the same sentence as DUSP4 in open-access papers (continued):
Sharing a sentence is not in itself a finding about the gene and the disease.
tumor (96 papers, 2007 to 2026). "From the scope of clinical tumor tissues, DUSP4 deficiency was also highly correlated with HCC prognosis and response to LVN." (PMID 37153782, 2023). "A statistically significant upregulation of DUSP4 expression levels in the KRAS-mutated tumours was detected (p = 0.048, Mann–Whitney test)." (PMID 37946160, 2023). "In our study, DUSP4 play as HCC tumor suppressor, while its deficiency also greatly cut down treating effect of Lenvatinib." (PMID 35864956, 2022). "Tumor suppressor genes Kmt2d and Dusp4 showed similar loss of interactivity of their promoters with putative H3K27Ac rich loci in Smc3/Bcl6 tumors." (PMID 34621263, 2021). "Immunohistochemical analysis showed that decreased DUSP4 expression was associated with the sex, tumour size, depth of invasion and distant metastasis in patients with GC." (PMID 27957827, 2017). "The clinicopathological correlation analysis revealed that DUSP4 expression was significantly associated with tumor size (P = 0.014) and higher T stage (P = 0.040)." (PMID 25688264, 2015). "Likewise, DUSP4 showed antitumour effects in GC, where IHC analysis of tumour specimens showed that DUSP4 downregulation is associated with enhanced tumour size, depth of invasion, and distant metastasis." (PMID 40943262, 2025). "We identified 9 genes whose increased expression was significantly associated with tumor size in female LC patients of which four code for MAPK signaling molecules (DUSP4, FGL1, TXNRD1, PLA2G4E), three for oncogenes (KRT16, STRIP2 and TNS4), tumor suppressor cystatin 5, and NQO1." (PMID 38245882, 2024). "The up regulated circFTO could sponge and block the function of miR-514b-3p, a reported tumor suppressor, and caused overexpression of DUSP4." (PMID 36127345, 2022). "In addition, the inhibition of DUSP4 suppressed the anti-tumor effect of Lenvatinib, indicating that DUSP4 deficiency is a critical driver for treatment failure." (PMID 35864956, 2022). "Genomic DUSP4 loss is a frequent event in many cancer types, indicating that DUSP4 may have tumour‐suppressive function." (PMID 27957827, 2017). "Dual specificity phosphatase 4 (DUSP4) has been associated with tumor progression." (PMID 29212207, 2017). "One study reported that decreased DUSP4 expression was associated with sex, tumor size, depth of invasion and distant metastasis in human GC, and that overexpression of DUSP4 reduced GC cell viability and invasive potential and induced cell apoptosis and S phase cycle arrest." (PMID 29212207, 2017). "It is also possible that loss of DOK2 on its own or in combination with loss of other tumor suppressors (e.g. DUSP4 which is located with DOK2 in the same frequently deleted locus at 8p21.3) is able to trigger a robust activation of the MAPK pathway hence favoring lung tumorigenesis." (PMID 24255704, 2013). "A subcutaneous tumor model using Dusp4-overexpressing cells in female C57BL/6J mice was established to evaluate DUSP4-mediated microenvironment remodeling and anti-PD-L1 therapy efficacy." (PMID 42073612, 2026). "Conversely, reduced DUSP4 levels correlate with aggressive gastric cancer progression, including higher tumor grade, metastatic spread, and diminished patient survival." (PMID 40630642, 2025). "Concurrently, relevant studies have clearly reported the promoting effect of DUSP4/CREB/PRKACB on tumor progression." (PMID 40630642, 2025). "It was then illustrated by qRT-PCR, WB, and a nude mouse model that DUSP4 inhibition enhanced tumor sensitivity to sorafenib, as demonstrated by tumor growth inhibition." (PMID 40612869, 2025). "In view of the findings of preceding studies, it was determined in the present study that FENDRR curtails persistent tumor growth by instigating the sinking of the DUSP4/CREB/PRKACB axis." (PMID 40630642, 2025). "Xenografts with restored expression of DUSP4 in PANC-1 cells with 8p loss showed longer survival and reduced tumour growth and metastasis compared with mice transplanted with WT PANC-1." (PMID 40943262, 2025).
tumor (continued). "We focused our analysis on CD8+ and DUSP4 CD4+ T cells since these proved to contain most tumor-reactive cells and had the highest dysfunction scores." (PMID 38181797, 2024). "Our findings align with previous studieshighlighting the importance of tumor suppressor function of DUSP4 in human malignancies." (PMID 38071325, 2023). "At the same time, DUSP4 reacted predominantly in the nuclei, but in part also aberrantly in the cytoplasm of tumours as it has been reported previously." (PMID 37946160, 2023). "Analyzes of the relationship between HHE genes and the tumor site in the colon region indicated that four genes, including DUSP4, ZIC2, CD55, and CLDN2 significantly increased in the cecum region (FDR < 0.01)." (PMID 36064367, 2022). "In BRAF or RAS mutant tumor cells, DUSP4, DUSP6, SPRY2, and SPRY4 tend to be highly expressed, allowing tumors to evade regular MAPK signaling pathway feedback." (PMID 36437939, 2022). "We and others have previously shown that DUSP4 is a potential tumor suppressor in basal-like or TNBC and is frequently lost or downregulated, leading to cancer stem-like phenotypes and activation of MAPK pathways." (PMID 35850776, 2022). "We noted that the DEGs between the two T-cell clusters were consistent with the DEGs identified between ERG+ and ERG− tumor cells, with FOSB, FOS, and JUN overexpressed in ERG+ tumor cells while CXCR6 and DUSP4 were overexpressed in ERG- tumor cells." (PMID 35013146, 2022). "In general, we confirmed a tumor promoter role of DUSP4 in ccRCC as a downstream target of miR-514b-3p." (PMID 36127345, 2022). "On the one hand, DUSP4 is reported to be a tumor suppressor that inhibits ERK1 and MAPK1 (ERK2) activity in the nucleus." (PMID 35382456, 2022). "While comparing with normal Tregs, tumor Tregs had increased expression of multiple genes related with immune suppression, including DUSP4, IL2RA, TNFRSF4, LAYN and LGALS1." (PMID 35664061, 2022). "Dual-specificity protein phosphatase 4 (DUSP4), a negative regulator of extracellular-regulated kinase activity, was a potential mediator of resistance to chemotherapy and a tumour suppressor." (PMID 35057823, 2022). "Further, ASCL2 was shown to indirectly affect tumor immune cell infiltration by negatively regulating the expression of DUSP4." (PMID 35774798, 2022). "Floxed Dusp4 mice were crossed with the MMTV-Neu-Ires-Cre (MMTV-NIC) luminal model of mammary tumorigenesis, which ensures Dusp4 deletion in Neu + tumor cells." (PMID 35850776, 2022). "This implies that ASCL2 can indirectly affect the tumor immune microenvironment by regulating the expression of downstream target gene DUSP4." (PMID 35774798, 2022). "SALL4 expression in adults is restricted to spermatogonia, and is required for long‐term maintenance of SSCs by repressing expression of Foxl1 and Dusp4, two tumour suppressor genes that inhibit SSCs growth and self‐renewal." (PMID 34296486, 2021). "Among genes with reduced enhancer-promoter loops were known tumor suppressors such as Tet2, Dusp4, as well as MHC class II genes." (PMID 34621263, 2021). "Using reporter gene assays, we found that the risk allele of CCV rs7461885 reduced the activity of a DUSP4 enhancer element, consistent with the function of DUSP4 as a tumour suppressor gene." (PMID 31936698, 2020). "The DUSP4 expression is related to tumor cells’ proliferation, apoptosis and metastasis, as well as tumor angiogenesis, for which DUSP4 gene is considered an oncogene." (PMID 32897241, 2020). "The results showed that decreased DUSP4 expression was correlated with gender (P = 0.037), tumour size (P = 0.020), depth of invasion (P = 0.008) and distant metastasis (P = 0.016)." (PMID 27957827, 2017). "DUSP4 is known to regulate cell survival and tumor progression, and overexpression induces senescence downstream of RB/E2F, thus placing CAPERα/TBX3 upstream of another p16/RB effector." (PMID 24876127, 2014).
tumor (continued). "For example, some DUSPs exhibit loss of heterozygosity in some cancers with additional functional studies supporting potential roles as tumor suppressors, including DUSP4, DUSP6 and DUSP7." (PMID 25568665, 2014). "Proteomic data from RPPA further indicate that KC1 tumours have the highest basal protein levels of DUSP4, suggesting that MEKi monotherapy could provide significant therapeutic benefit for this subtype." (PMID 41025426, 2025). "In addition, DUSP4 was previously shown to be highly expressed in tumor-enriched CD8+ clones of metastatic NSCLC tumors." (PMID 40187353, 2025). "A possible oncosuppressor role of DUSP4 has also been identified in head and neck SCC (HNSCC), in which the expression of G9A/EHMT2 histone methyltransferase was found to be associated with tumour growth and poor prognosis." (PMID 40943262, 2025). "Although several proteins (e.g., ACVRL1, DUSP4, PREX1) showed increased expression in the high-risk group, PD-L1 and p38 MAPK were prioritized for mechanistic validation due to their established roles in tumor-immune interactions." (PMID 41050683, 2025). "Specific to tumor cytotoxic T cells, DUSP4 was overexpressed relative to the liver and PBMCs." (PMID 40848148, 2025). "DUSP4 is implicated in the development of T cell exhaustion, and we also identified overexpression of several other classically defined exhaustion marker genes such as ENTPD1, IL2RA, and CXCR6, consistent with an immune-exhausted tumor microenvironment." (PMID 40848148, 2025). "Loss of DUSP4 in genome is a common occurrence in various cancer types, which suggests that DUSP4 may function as a tumor suppressor." (PMID 39125943, 2024). "DUSP4, on the other hand, was reported as a tumor suppressor." (PMID 38380329, 2024). "We did observe decreased pJNK and pp38 in DUSP4 knockouts, confirming previous observations and suggesting that downregulation of pJNK via DUSP4 mediates its tumor suppressive activities." (PMID 36991492, 2023). "Besides these genes, we also observed an upregulation of DUSP4 and 6 in comparing tumour samples and normal tissue." (PMID 37946160, 2023). "Since our in vivo screens used MEKDD expressing cells, we explored whether DUSP4 is a context-dependent tumor-suppressor." (PMID 36991492, 2023). "Also, we observed an increase of tumor proliferation and invasion in DUSP4 overexpressed ccRCC cells in vitro and in vivo." (PMID 36127345, 2022). "For example, DUSP4 is noted as a tumor suppressor due to its role in inhibiting MAPK signaling; however, we find increased dependency on DUSP4 in cell lines with activating mutations in BRAF suggesting that DUSP4 contributes to maintaining the balance of MAPK signaling in BRAF mutant tumors." (PMID 35382456, 2022). "Research shows that DUSP4 is a vital regulator of tumor development." (PMID 35774798, 2022). "Expression levels of seven CBX7 targets, namely Wnt10a, Ccne1, Fgfr2, Bhlhe22, Klhdc8a, Pde10a, and Dusp4, which had been significantly inhibited in miR-181ab1 KO compared to WT tumours in mice, were also significantly lower in either iClust2 or iClust3 than iClust1 HCCs." (PMID 35867177, 2022). "Meanwhile, ASCL2 might have an effect on tumor immune cell infiltration through an indirect mechanism by negatively regulating the expression of DUSP4." (PMID 35774798, 2022). "As a tumor suppressor, DUSP4 knockout is expected to result in decreased dependency." (PMID 35382456, 2022). "Negative DUSP4 expression in ccRCC patients was significantly associated with old age, high histologic grade, tumor necrosis, high pT category, and worse clinical outcomes." (PMID 34679636, 2021).
tumor (continued). "Although less well studied than DUSP1/MKP-1, there have nevertheless been numerous reports of either increased or reduced expression of DUSP4/MKP-2 in a wide variety of human cancer cell lines and primary tumours including pancreatic, lung, ovarian, breast, liver, thyroid and colon." (PMID 30401534, 2019). "As a negative regulator of the MAPK signaling pathway, DUSP4 may represent as a tumor suppressor gene." (PMID 29212207, 2017). "Interestingly, NOS2, a target of DUSP4, and DUSP4, both factors that stimulate tumour migration and invasion, are regulated by GFAP." (PMID 29152145, 2017). "Ideally, CyTOF could be used to compare the levels of phosphorylated ERBBs, phosphorylated AKT, and total DUSP4 levels in tumor and matched normal samples from each patient." (PMID 26084293, 2015). "DUSP4 plays a crucial role in regulating the tumor-relevant MAPK pathways." (PMID 25688264, 2015). "They concluded that DUSP4 expression was negatively correlated with factors reflecting tumor progression and suggested that DUSP4 may act as a tumor suppressor." (PMID 25688264, 2015). "Consistent with our own data, DUSP4 expression has previously been shown to be increased in pancreatic tumours with K-Ras mutations and DUSP6 expression increased in a variety of tumour types with mutations in Ras or Raf pathway genes." (PMID 20147967, 2010). "Thus, DUSP4 is a context-specific tumor suppressor that is dependent on the activity of GADD45B." (PMID 41523653, 2026). "Therefore, higher levels of DUSP4 would rather be suggestive of a function as a tumour suppressor." (PMID 37946160, 2023). "Moreover, lentiviral reconstitution of DUSP4 (human sequence) or phosphatase-dead DUSP4 (DUSP4PD) into Dusp4-deficient DPM tumor cells did not suppress tumor formation in nu/nu mice, though growth rate was modestly impacted." (PMID 35850776, 2022). "Despite an absence of correlation with metastatic risk in UM, DUSP4 plays a complex role in oncogenesis as previously reported in other cancers, acting as both a proto-oncogene or tumor suppressor, with effects on cell survival and proliferation depending on tissue and molecular subtype." (PMID 36576731, 2022). "Additionally, The KO-DUSP4 group also showed enhanced tumor growth compared to the KO-NC group, implying that DUSP4 might be a tumor suppressor." (PMID 35864956, 2022). "However, some studies reported that DUSP4 acted as a tumor suppressor." (PMID 34679636, 2021). "Therefore, DUSP4 plays a biological role in tumor promotion, but Smad4 might act a suppressive effect." (PMID 32897241, 2020). "Interestingly, blocking IL-4 suppressed BCSCs proliferation, colony forming efficiency and in vivo tumor formation, while it supported the expression of the dual specificity phosphatase-4 (DUSP4) in triple-negative basal-like BCSCs, leading to aggressiveness reduction." (PMID 28927416, 2017). "Some reports have also described that DUSP4 may play a tumor suppressor role." (PMID 25688264, 2015). "Further, by blocking the MAPK cascade, DUSP4 could act as a candidate tumor suppressor gene." (PMID 25226156, 2014). "Several candidate tumor suppressor genes have been identified from 8p including DLC-1 (8p21.3-22), FEZ1 (8p22), liver-related putative tumor suppressor (LTPS) gene (8p23), PCM1(encoding a centrosomal protein) and DUSP4/MKP-2 (encoding a MAP kinase phosphatase)." (PMID 17784942, 2007). "In fact, SULF2 is involved in Wnt-driven tumor progression, PLAUR in extracellular matrix remodeling and migration, DUSP4 in sustaining epithelial–mesenchymal plasticity, and ATP6V0A4/V-ATPase-dependent acidification in invasive phenotypes." (PMID 41596301, 2026). "During tumour progression, the RAS–RAF–MEK1/2–ERK1/2 pathway was consistently activated, along with upregulation of DUSP4, DUSP6, and the cancer stem cell marker CD133." (PMID 40943262, 2025).
tumor (continued). "Therapeutically, the KC1 tumours exhibit significant sensitivity to MEK inhibitors, likely due to the elevated expression of DUSP4/6 and ETV4, key regulators of the MAPK signalling pathway." (PMID 41025426, 2025). "Mechanistically, FENDRR has been demonstrated to induce the sinking of the DUSP4/CREB/PRKACB signaling pathway and reverse the epithelial–mesenchymal transition (EMT) pathway, thereby inhibiting tumor growth." (PMID 40630642, 2025). "Consistently, ulixertinib-treated PDX tumours displayed increased HER2 and p-ERK1/2, and decreased DUSP4 and DUSP6 IHC staining." (PMID 38509064, 2024). "Our findings suggest that ARID1A protein transcriptionally modulates DUSP4 expression by remodeling chromatin, subsequently inactivating the MAPK pathway, leading to tumor suppression." (PMID 38071325, 2023). "Ectopic DUSP4 expression decreased cell proliferation, and pharmacologically inhibiting the MAPK pathway significantly mitigated tumor formation in vivo." (PMID 38071325, 2023). "ACE2 was homogenously expressed in primary tumor samples from CRC-Liver group, while CLDN18 and DUSP4 were homogenously expressed in Peritoneum samples with a Log2 fold change of −3.267, 4.891 and 2.764 respectively." (PMID 37686695, 2023). "We found that 3.8% of top down-regulated DEGs in GKO tumours were CBX7 targets, including Wnt10a, CCNE1, FGFR2, and DUSP4." (PMID 35867177, 2022). "This study further reinforces the complexities of the role of DUSP4 in the MAPK signaling pathway and highlights potential tumor-intrinsic adaptive mechanisms for the control of intracellular signaling cascades by phosphatases." (PMID 36576731, 2022). "Of these, DHRS3, DUSP4, GAN, RGS12, and TRIM14 are known oncogenes or tumor suppressors (as indicated by CancerMine)." (PMID 33849068, 2021). "Marked overexpression of DUSP4, CD44, MUM1/IRF4, BCL-2, CD146/MUC18, IGF1R, and AKT3 was observed in the tumour cells in all mUM, compared to the background hepatocytes." (PMID 33008022, 2020). "Compared to the expression levels in normal tissue, other genes, such as ADRB3, BTG2, DUSP4, RAD51 or FBLX7, were downregulated in specific tumor types, and ANG, ESD and STL7 were downregulated in most tumor types." (PMID 31159852, 2019). "One of the most prominent hits in this screen was dual specificity phosphatase-4 (DUSP4), a well-established tumor suppressor that negatively regulates JUN N-terminal kinase JNK." (PMID 30482246, 2018). "We must highlight that DUSP1, DUSP4, and DUSP6 have pleiotropic roles as both oncogenes and tumour suppressors in various cancers." (PMID 26859151, 2016). "Unfortunately, we were unable to obtain tumor specimens from these two responders to further investigate their ERBB and/or DUSP4 status." (PMID 26084293, 2015). "Current studies indicate that DUSP2, DUSP4 and DUSP16 are involved in the co-adjustment between ERK1/2 and JNK, with these reports focusing on tumor cells and immune response." (PMID 25019380, 2014). "For example, DOK2 lies telomeric to DUSP4, a MAP-kinase phosphatase which negatively regulates MAPK signaling downstream of RAS and has been identified as a candidate tumor suppressor gene." (PMID 24255704, 2013). "In the absence of commercially available DUSP5 antibodies, the authors further studied DUSP4/MKP-2 in detail, revealing it as a potential regulator of ERK-driven tumour cell proliferation." (PMID 22812510, 2013). "snRNA‐seq analysis revealed that among DUSP4, DUSP6 and ETV4, only DUSP4 was exclusively expressed by cancer cells, making it a more specific biomarker for KC1 tumours, highlighting DUSP4 as a more specific biomarker of KC1 tumours." (PMID 41025426, 2025). "However, only levels of SOX4 and DUSP4 were reduced after PD1-blockade, where there is expected reactivation of tumor-targeting clones and reduction in the exhaustion phenotype." (PMID 36973261, 2023).